DNAJB1 (DnaJ heat shock protein family (Hsp40) member B1)
Diseases named in the same sentence as DNAJB1 in open-access papers (continued):
Sharing a sentence is not in itself a finding about the gene and the disease.
cancer (continued). "Moreover, the recent identification of other cancer entities that express the DNAJB1-PRKACA fusion transcript gives the prospect that targeting the fusion protein might improve treatment options in multiple cancer entities." (PMID 36302754, 2022). "Despite differences in the chemical properties of bortezomib, MG-132, and MLN-2238, treatment with these PIs led to the recurrent dysregulation of 12 genes (e.g. BAG3, DNAJB1, HMOX1) in cell lines representing multiple cancer types." (PMID 39138277, 2024). "In cancers where HSPA4 expression significantly impacts prognosis, four genes—HSP90AA1, HSPA8, DNAJB1, and HSP90AB1—demonstrated a pronounced correlation." (PMID 38305786, 2024). "Heat-shock family genes involved in HSF1 transactivation (e.g. HSPA1A, DNAJB1 and HSP90AB1) were also significantly enriched in this module, which has been shown previously to regulate cancer-mediated fibroblast activation." (PMID 36720863, 2023). "As DnaJB1 positively regulates the epidermal growth factor receptors (EGFR) signaling, knockdown of DnaJB1 promotes the sensitivity of tumor cells to anti-cancer effects of the EGFR inhibitor gefitinib in human lung epithelial adenocarcinoma cells." (PMID 31878360, 2019). "We further divided cancer cells into six subsets, fibroblasts into six subsets, and immune cells into monocytes (Cd14+ monocytes, M1 macrophages, M2 macrophages, and DCs) and T cells (CD8+ T cells, CD4+ T cells, Dnajb1 high cells, and Dnajb1 low cells)." (PMID 39840525, 2025). "Crucially, upon evaluating genes that may significantly influence cancer prognosis, HSP90AA1, HSPA8, DNAJB1, and HSP90AB1 manifested pronounced correlations with HSPA4 expression." (PMID 38305786, 2024). "Fifty of fusion genes have been reported and 14 involving known cancer genes (ALDH2-ACAD10, BIRC6-SPAST, BIRC6-TTC27, CGNL1-TCF12, CPEB3-IDE, CTNNA1-KDM3B, DNAJB1-PRKACA, LRP5-CHKA, PPFIBP1-STK38L, RNF213-SLC26A11, RXRA-WDR5, SEC16A-NOTCH1, WNK1-ERC1, and ACVR1B-ACVRL1)." (PMID 37403120, 2023). "Functional validation of the DNAJB1-PRKACA fusion and genes in the mRNA and lincRNA signature in the context of FLC may reveal novel therapeutic targets of this rare and deadly cancer." (PMID 28304380, 2017). "Although this mechanism has not been yet reported in cancer cells, it is worthy of note that Hsp-40, also known as DNAJB1, and the other members of DNAJ family have been found to be involved in the regulation of cancer cells and CSCs." (PMID 25566187, 2014).
cancer (continued). "To examine differentially expressed genes in FLC, we performed RNA-seq on an expanded set (Cohort 1) of FLC patient tumors (n = 35) and matched non-malignant liver (NML, n = 10) from the Fibrolamellar Cancer Foundation biobank, and confirmed DNAJB1-PRKACA (DP fusion) expression in all tumor samples." (PMID 38512964, 2024).
tumor (67 papers, 2007 to 2026). "DNAJB1, which belongs to the heat shock 40 protein family is associated with autophagy and participates in tumour progression." (PMID 35459137, 2022). "This suggests that high expression of DNAJB1 in naive T-cells within the tumor microenvironment induces stress, thereby influencing the differentiation and function of naive T-cells." (PMID 41186645, 2026). "The C2 cluster (heat shock proteins and molecular chaperones) showed high expression of HSPA1B and DNAJB1, suggesting that tumor cells experience high biological stress and rely on these proteins to maintain protein folding homeostasis." (PMID 40463392, 2025). "This study found that lobeline enhances the presence of CD14+ monocytes, DCs, and Dnajb1 high cells in the tumor microenvironment while reducing the number of Dnajb1 low cells." (PMID 39840525, 2025). "DNAJB1-PRKACA fusion transcripts were detected by polymerase chain reaction in both the FLC tumor samples obtained and patient-derived organoids, and DNAJB1-PRKACA fusion proteins were detected using probes." (PMID 39192365, 2024). "The oncogenic fusion protein DNAJB1-PRKACA represents an attractive target for the development of novel therapies for this devastating tumor disease." (PMID 36302754, 2022). "Further comprehensive analysis based on TCGA data indicated that the expression level of 3 genes (AVEN, DAZAP2, DNAJB1) were significantly higher in GC tumor tissues than in normal tissues." (PMID 36465351, 2022). "Taken together with our histological and RNA marker analyses, we conclude that all six tumor samples expressing DNAJB1-PRKACA display features consistent with FLC." (PMID 28304380, 2017). "In our analyses, we detected robust evidence of DNAJB1-PRKACA expression in six tumor samples all classified as Liver Hepatocellular Carcinoma." (PMID 28304380, 2017). "RNA-seq analysis confirms the presence of a fusion transcript (DNAJB1-PRKACA) characteristic of hFL-HCC tumours." (PMID 26437858, 2015). "The elevated expression of HSPs such as HSPD1, HSPE1, HSPA1A, HSPA6, and DNAJB1 suggests that naïve T-cells in tumor tissues may be under a state of stress or heat shock." (PMID 41186645, 2026). "Inhibition of DNAJB1 increased the proliferation and tumor growth of MCF-7 cells." (PMID 39165691, 2024). "Moreover, we unveiled co‐occurrence relationships among ITSGs in tumour mutations, such as TIPARP with DDX3X and HERPUD1 with DNAJB1." (PMID 39031800, 2024). "The DNAJB1–Hsp70 complex is a potential valuable target for tumor treatment." (PMID 34307121, 2021). "The fibrolamellar variant of HCC (FHCC) is due to a heterozygous deletion on chromosome 19 that encodes a functional chimeric protein (DNAJB1-PRKACA) and characterized by being less aggressive with a normal alpha-fetoprotein (AFP) tumour marker and a female predominance." (PMID 30305894, 2018). "Increased expression of endoplasmic reticulum stress-induced transcripts such as PPP1R15A (GADD34), heat shock proteins HSPA6 and DNAJB1, and the stress-related transcription factor DDIT3 were observed in BRAFMT tumours with the highest-risk of disease relapse." (PMID 29568398, 2018). "Some studies have also found that the Dnajb1 gene may be related to tumor immune tolerance." (PMID 39840525, 2025). "First, our study showed that naïve T-cells in tumor tissues exhibit increased expression of HSPs, including HSPD1, HSPE1, HSPA1A, HSPA6, and DNAJB1." (PMID 41186645, 2026).
tumor (continued). "Genes associated with MAPK signaling cascades, a major downstream pathway of EGFR signaling (AREG, JUN, DNAJB1, DUSP1), were upregulated in tumor C0 NK cells." (PMID 41082397, 2026). "We then investigated how the transcriptomes of the engineered organoid models mimicking the two FLC genetic backgrounds (i.e. DNAJB1-PRKACAfus and BAP1KO;PRKAR2AKO) compared with those from FLC tumor tissues." (PMID 37137901, 2023). "TIMER analysis showed that DNAJB1, COL10A1, PTGS2, AFP, and EGF were correlated with tumor-infiltrating lymphocytes." (PMID 36967783, 2023). "In FL-HCC, the DNAJB1-PRKACA fusion transcript is detectable in 100% of patients and has been identified as the oncogenic driver in tumor pathogenesis indicating expression of the fusion transcript in all tumor cells." (PMID 36302754, 2022). "The expression levels of DNAJB1, DNAJB5, DNAJB6, DNAJB11, DNAJB12, DNAJB13, and DNAJB14 were significantly upregulated in the tumor tissues." (PMID 32984053, 2020). "A signature feature of most primary hFL-HCCs is the expression of a fusion transcript, DNAJB1-PRKACA18, 19, which was shown recently in a study of 78 primary tumours to be present in at least ∼80% of FL-HCCs20." (PMID 26437858, 2015). "Additionally, genes involved in the cellular response to stress were commonly upregulated in tumor C1 and C2 NK cells (HSP90AA1, HSPA1B, HSPH1, DNAJB1, PSMB9, CSTP1)." (PMID 41082397, 2026). "The DNAJB1-PRKACA fusion transcript was recently detected as the oncogenic driver of tumor pathogenesis in almost 100% of FL-HCC patients and thus represents an attractive target for the development of novel therapies for this devastating tumor disease." (PMID 38606105, 2024). "The heatmap showed that 12 tumor suppressors formed into two clusters: cluster 1 contains seven downregulated tumor suppressors including PTEN, PSME1, DNAJB1, HSPH1, DEDD2, PAK1IP1, and MIR1244-3; and cluster 2 contains five upregulated tumor suppressors (OSGIN1, IFI27L1, MTCH2, NKD2, and IBTK)." (PMID 34571936, 2021). "However, expression levels of DNAJB1 (p = 0.018), HSPB2 (p < 0.001), HSPB6 (p < 0.001) and HSPA1A (p = 0.021) were significantly lower in tumor tissues." (PMID 31222140, 2019). "We observed this fusion transcript in 26 of 26 tumor specimens from 15 FL-HCC patients, further strengthening the hypothesis of the DNAJB1-PRKACA fusion in tumorigenesis." (PMID 28486549, 2017). "We analysed the sequencing data using MapSplice2 and detected DNAJB1-PRKACA with high confidence in all four tumour samples of the hFL-HCC tumour line, but not in any of the hAHEPs." (PMID 26437858, 2015). "In addition, tumor molecular profile analyzes showed that proliferation and mitogenic signaling pathways were enhanced in FLC tumor cells, and the activation of the WNT signaling pathway cooperated with the expression of DNAJB1-PRKACA to accelerate FLC formation." (PMID 39582856, 2024). "Overexpression of the DNAJB1-PRKACAfus or endogenous recreation of the fusion by CRISPR-Cas9 could initiate liver tumor development in mice, providing indications that the hepatocyte could constitute the cell-of-origin, but tumor latency was long." (PMID 37137901, 2023). "Eight genes were significantly mutated only when both C1 and C2 clusters were combined in a single analysis, while a further two genes (MAGEB6 and DNAJB1) were categorised as SMGs in the C1 cluster but were no longer significant when C2 tumours were included in the analysis." (PMID 36207323, 2022). "DNAJB1-PRKACA-derived HLA class I and HLA class II ligands induce multifunctional cytotoxic CD8+ and T-helper 1 CD4+ T cells, and their cellular processing and presentation in DNAJB1-PRKACA expressing tumor cells is demonstrated by mass spectrometry-based immunopeptidome analysis." (PMID 36302754, 2022).
tumor (continued). "Finally, we detected the DNAJB1-PRKACA chimera in the hFL-HCC tumour line and in the primary hFL-HCCs but not in any maturational lineage stage of the normal hepatic parenchymal cells, confirming that it is uniquely expressed in hFL-HCCs." (PMID 26437858, 2015). "The most consistent biological finding to date in FL-HCC is the recently described DNAJB1-PRKACA fusion transcript, which has been detected in all tumor samples (and no normal liver samples) studied thus far." (PMID 28486549, 2017).
infection (34 papers, 2008 to 2025). The state of being infected such as from the introduction of a foreign agent such as serum, vaccine, antigenic substance or organism. "Immunoblot analysis showed that the NP levels decreased dramatically in Hsp40/DnaJB1 siRNA treated cells at different time points post-infection." (PMID 26750153, 2016). "As reported, DNAJB1 has been shown to be down-regulated during the infection of influenza A virus, but not SARS-CoV-2." (PMID 33505977, 2020).
neurodegenerative disease (21 papers, 2012 to 2025). A disorder of the central nervous system characterized by gradual and progressive loss of neural tissue and neurologic function. "JDPs have previously been implicated in various neurodegenerative diseases, with prior work suggesting that DnaJA2, DnaJB1, and DnaJB4 suppress tau aggregation in vitro." (PMID 37387473, 2023). "DNAJB1/HDJ1 is involved in neurodegenerative diseases, inflammation, and viral replication through binding to proteins involved in these diseases." (PMID 34948322, 2021). "HSPs, including HSP90AA1, HSPA8 and DNAJB1 (all upregulated in the presence of P2RY6 antagonist) are key players in chaperone-mediated autophagy (CMA), a form of autophagy that is impaired in aging and neurodegenerative diseases." (PMID 36203578, 2022).
DNAJB1 also shares sentences with these, for which no sentence is quoted: viral infection (16 papers); malaria (10); prostate carcinoma (9); Obesity (7); rheumatoid arthritis (6); COVID-19 (5); colorectal cancer (4); glioma (4); melanoma (4); myopathy (4); osteosarcoma (4); protein misfolding diseases (4); Alzheimer disease (3); amyotrophic lateral sclerosis (3); bacterial infection (3); Hypoglycemia (3); limb-girdle muscular dystrophy (3); Parkinson's (3); type 2 diabetes (3); amyloid (2); brain tumor (2); diabetes (2); dilated cardiomyopathy (2); glaucoma (2); head and neck squamous cell carcinoma (2); hepatoblastoma (2); HIV-1 infection (2); juvenile arthritis (2); lung squamous cell carcinoma (2); lymphoma (2).
A further 71 diseases each share a sentence with DNAJB1 in 2 papers or fewer.